PRSS37 (serine protease 37)
Description:
Plays a role in male fertility (By similarity). May have a role in sperm migration or binding to zona-intact eggs (By similarity). Involved in the activation of the proacrosin/acrosin system.
Synonyms: TRYX2
Tractability: Antibody: UniProt places it where antibodies can reach, with high confidence; UniProt predicts a signal peptide or a membrane-spanning region; its Gene Ontology location is reachable by antibodies, with medium confidence.
Gene: Protein-coding gene on chromosome 7 (141,836,300 to 141,841,487, reverse strand). Ensembl gene ENSG00000165076.
Subcellular location: Cytoplasmic vesicle, secretory vesicle, acrosome; Secreted
Gene Ontology:
Molecular function: serine-type endopeptidase activity
Biological process: positive regulation of acrosome reaction; regulation of protein processing; binding of sperm to zona pellucida; cell migration; positive regulation of fertilization; protein maturation; positive regulation of reproductive process; proteolysis
Cellular component: acrosomal vesicle; nucleus; extracellular region; secretory granule
Genetic constraint (gnomAD): Loss-of-function variants: 24 observed, 28.38 expected, observed/expected ratio (o/e) 0.85, 90% interval 0.61 to 1.19. The upper end of that interval is the gene's LOEUF score, 1.19, which puts it in group 5 of 6, group 1 being the genes least tolerant of losing a copy. Missense variants: 280 observed, 305.96 expected, observed/expected ratio (o/e) 0.92, 90% interval 0.83 to 1.01. Synonymous variants: 109 observed, 112.3 expected, observed/expected ratio (o/e) 0.97, 90% interval 0.83 to 1.14.
Homologues: Orthologues: chimpanzee PRSS37 (99% identical), macaque PRSS37 (97% identical), rabbit PRSS37 (89% identical), dog PRSS37 (86% identical), pig PRSS37 (84% identical), mouse Prss37 (83% identical), rat Prss37 (81% identical), guinea pig PRSS37 (80% identical). Paralogues in human: KLK15 (30% identical), KLK9 (29% identical), PRSS33 (29% identical), PLG (28% identical), GZMM (26% identical), PLAT (26% identical), PRSS48 (26% identical), PRSS27 (24% identical), OVCH1 (23% identical), PRSS57 (23% identical), TMPRSS12 (23% identical), PRSS50 (21% identical), and 2 more.
Diseases named in the same sentence as PRSS37 in open-access papers:
PRSS37 is named in the same sentence as 3 diseases in open-access papers, as found by Europe PMC text mining. Sharing a sentence is not in itself a finding about the gene and the disease. The quoted sentences say what the papers report.
male infertility (3 papers, 2020 to 2025). The inability of the male to effect fertilization of an ovum after a specified period of unprotected intercourse. "Although PRSS37 is an inactive protease, loss of Prss37 causes male infertility in mice because the KO spermatozoa fail to migrate to the oviduct; ADAM3 vanishes in Prss37 KO spermatozoa due to problems in ADAM3 modification." (PMID 32529245, 2020).
PRSS37 also shares sentences with these, for which no sentence is quoted: cancer (1 paper); infertile (1).